MSANTD1 (Myb/SANT DNA binding domain containing 1)
Synonyms: C4orf44; LOC345222
Tractability: No criterion of Open Targets' tractability assessment is met for any kind of drug.
Gene: Protein-coding gene on chromosome 4 (3,244,369 to 3,271,738, forward strand). Ensembl gene ENSG00000188981.
Subcellular location (Human Protein Atlas): Nucleoplasm; Cytosol
Gene Ontology:
Biological process: positive regulation of DNA-templated transcription
Cellular component: nuclear body
Genetic constraint (gnomAD): Loss-of-function variants: 7 observed, 17.93 expected, observed/expected ratio (o/e) 0.39, 90% interval 0.22 to 0.73. The upper end of that interval is the gene's LOEUF score, 0.73, which puts it in group 3 of 6, group 1 being the genes least tolerant of losing a copy. Missense variants: 384 observed, 377.87 expected, observed/expected ratio (o/e) 1.02, 90% interval 0.93 to 1.11. Synonymous variants: 177 observed, 163.56 expected, observed/expected ratio (o/e) 1.08, 90% interval 0.96 to 1.23.
Homologues: Orthologues: macaque MSANTD1 (94% identical), chimpanzee MSANTD1 (92% identical), mouse Msantd1 (89% identical), guinea pig MSANTD1 (88% identical), rat Msantd1 (87% identical), dog MSANTD1 (86% identical), pig MSANTD1 (85% identical), rabbit MSANTD1 (85% identical), tropical clawed frog MSANTD1 (70% identical), zebrafish msantd1 (47% identical), Drosophila melanogaster CG7239 (17% identical), Drosophila melanogaster ssp (17% identical), and 2 more.
Diseases named in the same sentence as MSANTD1 in open-access papers:
MSANTD1 is named in the same sentence as 2 diseases in open-access papers, as found by Europe PMC text mining. Sharing a sentence is not in itself a finding about the gene and the disease. The quoted sentences say what the papers report.
Stillbirth (1 paper, 2019). Death of the fetus in utero after at least 22 weeks of gestation. "We identified 12 genome-wide significant associations between these traits and genetic loci, including variants near CACNA2D3 with gestation length, MSRB3 and MSANTD1 with litter size, SMOC2 with cesarean section rate and UFM1 with stillbirth rate." (PMID 31263560, 2019).
MSANTD1 also shares sentences with these, for which no sentence is quoted: Epileptic encephalopathy (1 paper).